CCL2 (C-C motif chemokine ligand 2)
Diseases named in the same sentence as CCL2 in open-access papers (continued):
Sharing a sentence is not in itself a finding about the gene and the disease.
esophageal squamous cell carcinoma (14 papers, 2008 to 2025). Esophageal squamous cell carcinoma (ESCC) is a type of esophageal carcinoma (EC) that can affect any part of the esophagus, but is usually located in the upper or middle third. "For instance, CCL2 production by esophageal squamous cell cancers was associated with increased infiltration of tumor-associated macrophages." (PMID 39809756, 2025). "The increase of CCL2 expression during the carcinogenesis of esophageal squamous cell carcinoma (ESCC) is related to the accumulation of TAMs, both of which indicate a poor prognosis of esophageal cancer." (PMID 33391402, 2021). "Paradoxically, increased expression of CCL2, a molecule that interacts with CCR2, has been linked to the accumulation of tumor-associated macrophages in esophageal squamous cell carcinoma (ESCC)." (PMID 38755605, 2024). "Also, CCL2 was reported to recruit Tregs in the progression of esophageal squamous cell carcinoma." (PMID 33329712, 2020). "Studies have demonstrated that CCL2 expression levels are significantly elevated in various tumor tissues and their TMEs, including CRC and esophageal squamous cell carcinoma (ESCC)." (PMID 40463500, 2025). "In esophageal squamous cell carcinoma (ESCC), IL-33 stimulated the production of CCL2 through TGF-β involving Treg cell recruitment." (PMID 34209038, 2021).
Lewis lung carcinoma (14 papers, 2015 to 2025). "The decreased muscle strength and fat mass associated with high-dose CCL2 are consistent with trends observed during cancer cachexia, as demonstrated in the 4T1 model here and in the Lewis lung carcinoma model." (PMID 38973385, 2024). "For example, tumour cells are the major source of CCL2 in Lewis lung carcinomas while B16 cells express low level of CCL2." (PMID 29020102, 2017). "Lewis lung carcinoma (LLC)-conditioned BMDMs also showed a significant increase in TNFα and CCL2 levels in response to LPS." (PMID 26177198, 2015).
renal cell carcinoma (14 papers, 2016 to 2024). "In renal cell carcinoma, CCL2 secreted by M2 macrophages increases muscleblind like splicing regulator 2 (MBNL2) expression, which in turn stabilizes B-cell lymphoma 2 (Bcl-2) mRNA, leading to the inhibition of Beclin 1-dependent autophagy and endowing RCC cells with invasion properties." (PMID 39286635, 2024). "Among the mentioned chemokines, the expression of CCL2 has been evaluated in different in vivo studies and cancer patients suffering from prostate, breast, ovarian, gastric, melanoma, and renal cell carcinoma (RCC)." (PMID 38360737, 2024). "In renal cell carcinoma (RCC), TAMs produce high levels of lipid-derived 15-hydroxyeicosatetraenoic acid through the enzymatic activity of 15-lipoxygenase 2 (15-LOX2), which positively correlates with CCL2 and IL-10 secretion, supporting pro-tumoral inflammation." (PMID 32823961, 2020). "Renal cell carcinoma, a typical immune-excluded tumor, is considered to lack the expression of some chemokines related to T cell recruitment, such as CXCL9, CXCL10, CXCL11, CXCL13, CX3CL1, CCL2, and CCL5, in its TME, but the specific mechanisms underlying this lack of chemokines remain unclear." (PMID 36397015, 2022).
Splenomegaly (14 papers, 2010 to 2025). Abnormal increased size of the spleen. "By further comparing the differences between antagonist and knockout models, it was evident that CCL2/CCR2 antagonists did not improve splenomegaly, lymphadenopathy, and circulating total/autoantibodies, suggesting the local involvement of CCL2/CCR2 in autoimmune target tissues, such as the kidney." (PMID 27403037, 2016).
brain tumors (13 papers, 2012 to 2024). "Our results indicate increased T cell-recruiting/activating cytokines CXCL10 and CCL2 both in serum and the brain tumor milieu." (PMID 36959214, 2023). "Furthermore, we analyzed the correlation between proteasome activity and IL-8, CCL2, NF-κB1 and NF-κB2 concentrations, which impact on brain tumors has already been indicated." (PMID 32886667, 2020). "These CCL2+ areas were seen to present the specific infiltration of CD3+ T-cells in brain tumors." (PMID 22319587, 2012). "In brain tumor patients the 20S proteasome ChT-L activity showed a positive correlation with only IL-8 concentration (r = 0.508; p = 0.0031); we did not observe a relationship between the 20S proteasome ChT-L activity and CCL2, NF-κB1 as well as the NF-κB2 concentration (p>0.05)." (PMID 32886667, 2020). "Therefore, the manipulation of CCL2 may be one of the particular therapeutic targets to control the infiltration of lymphocytes in brain tumors." (PMID 22319587, 2012). "Furthermore, CCL2 and its related receptor (CCR2) play an important role in brain tumors and are involved in regulating the migration of monocytes into the vascular endothelium." (PMID 35370869, 2022). "Serum CCL2 concentration was statistically lower in brain tumor patients compared to the non-tumoral group (p<0.001)." (PMID 32886667, 2020). "CCL2 concentration was analyzed in 32 brain tumor patients and 10 control individuals (in 1 case we did not have a sufficient serum volume to conduct analysis)." (PMID 32886667, 2020). "However, particularly in brain tumors, GFAP+CCL2+ cells adopt convoluted shapes, and CCL2 expression displays different, irregular patterns, depending on the anatomical complexity of the tumor." (PMID 23641198, 2013).
coronary atherosclerosis (13 papers, 2007 to 2024). Atherosclerosis of the coronary vasculature. "A previous study in the MACS found that elevated CCL2 and sCD163 levels were associated with subclinical coronary atherosclerosis." (PMID 30946765, 2019). "Also, monocyte chemoattractant protein-1 (MCP-1; or C-C Motif Chemokine Ligand 2, CCL2) gene −2578A > G polymorphism has been associated with an increased risk of coronary atherosclerosis in an asymptomatic population." (PMID 38732608, 2024).
gastritis (13 papers, 2014 to 2026). Inflammation of the stomach. "In gastritis, especially chronic gastritis caused by H. pylori, the role of CCL2 is particularly prominent." (PMID 41376630, 2025). "Among which, interleukin- (IL-) 6 (IL-6) and CC-chemokine ligand 2 (CCL2), as members of 15 common genes, have been reported to be associated with the progression of gastritis." (PMID 34471638, 2021). "In addition, Campylobacter concisus and Campylobacter rectus were recorded to upregulate genes such as immune factors, cytokines and CCL2, which were associated with the Hot Syndrome of gastritis in TCM." (PMID 30478535, 2019). "CCL2 was expressed in macrophages in H. pylori infected gastritis, and stimulation with lipopolysaccharide induced expression of the CCL2 in cultured macrophage RAW264.1." (PMID 24416340, 2014). "A recent study using network-based systems biology approach revealed that with leptin as a biomarker, gastritis patients with cold syndrome experienced low levels of energy metabolism, while the CCL2/MCP1 biomarker indicated that immune regulation was intensified in heat syndrome patients." (PMID 24701240, 2014). "The verification results of the GSE5081 dataset displayed that IL-6 and CCL2 were significantly upregulated in gastritis compared to normal, which was consistent with the results in the GSE60427 dataset." (PMID 34471638, 2021). "Apart from these genes, targets like CCL2, IL6, JAK2, IL2RA and CXCR1 were also of vital importance in the Hot herbs’ targets network, which might infer us that another potential mechanism of Hot herbs against Cold ZEHNG gastritis was to regulate immune responses." (PMID 39367502, 2024).
joint disease (13 papers, 2012 to 2025). "Thus, our evidence showing that nesfatin-1 induces increases in CCL2 expression provides a new insight into adipokine involvement in joint disease." (PMID 36594093, 2023). "With the emergence of targeted therapies for various chronic inflammatory diseases, such as RA and OA, focusing on the CCL2/CCR2 axis and its clinical implications can offer new perspectives on how to manage these common and debilitating joint diseases." (PMID 39076996, 2024).
malignant glioma (13 papers, 2005 to 2024). A grade III or grade IV glioma arising from the central nervous system. "It was expected to noninvasively predict CCL2 expression levels in malignant glioma tissues by magnetic resonance imaging (MRI)‐based radiomics and assess the association between the developed radiomics model and prognostic indicators and related genes." (PMID 39030882, 2024). "CCL2 concentrations in CSF samples from patients with malignant gliomas were significantly elevated in comparison with patients with benign or no tumors." (PMID 32456359, 2020). "The CCR2/CCL2 pathway is considered a relevant signal for the recruitment of TAMs and has been suggested as a therapeutic target in malignant gliomas." (PMID 32668709, 2020). "Based on these findings, we hypothesized that in GSCs and a GSC-bearing malignant glioma model, modulation of the CCL2/CCR2 and CXCL10/CXCR3 axes by celecoxib might contribute to antitumor effects." (PMID 32943658, 2020). "Malignant glioma secretes CCL2 or monocyte chemoattractant protein-1 (MCP-1) to stimulate monocytes to migrate to the tumor site where they are converted into immunosuppressive tumor-associated macrophages and myeloid-derived suppressor cells (MDSCs) and facilitates tumor growth." (PMID 23133490, 2012). "This is the first study showing that the suppression of the CCL2/CCR2 and CXCL10/CXCR3 axes by celecoxib may attribute to antitumor effects in a mouse malignant glioma model, in addition to intrinsic and extrinsic apoptotic induction by celecoxib in GSCs." (PMID 32943658, 2020). "Human monocyte chemoattractant protein-1 (MCP-1/CCL2) was isolated from the culture supernatants of not only mitogen-activated peripheral blood mononuclear leukocytes but also malignant glioma cells based on its in vitro chemotactic activity toward human monocytes." (PMID 37208442, 2023). "Furthermore, significantly higher CCL2 levels were observed in CSF samples from patients with subarachnoid spreading of malignant glioma than in those from patients without dissemination." (PMID 32456359, 2020).
renal dysfunction (13 papers, 2015 to 2025). "In this work, the highest levels of IL-6, CCL2 gene expression and IL-10 release and the lowest transcript levels of CCR2, which reflects monocyte maturation, have been observed after treatment with IS at concentrations found in subjects with moderate renal dysfunction." (PMID 26925780, 2016).
thyroid cancer (13 papers, 2016 to 2025). "It has been demonstrated that conditional activation of oncogenic BRAF in mouse results in the induction of thyroid cancers with increased CCL2 and CSF1 expression, associated with the recruitment of tumour-associated macrophages (TAMs)." (PMID 34299284, 2021). "Thyroid carcinoma cells secrete chemokines such as CCL2 and CXCL8 to recruit immunosuppressive cells (e.g., TAMs), creating an immune escape microenvironment." (PMID 40823082, 2025). "Vitamin D differently modulated the secretion of CCL2 and CXCL8, by significantly inhibiting the secretion of CCL2 in both thyroid cancer cell lines and inhibiting the secretion of CXCL8 only in TPC-1 (ANOVAs p < 0.05)." (PMID 35498406, 2022). "Previous in vitro and in vivo results showed that the reduction of CXCL8 and CCL2 secretion inhibits some of the pro-tumorigenic effects mediated by both these chemokines in thyroid cancer." (PMID 35498406, 2022). "CCL2 was discovered to be produced by several tumor cells including thyroid cancer cells, and hence its known functions include regulation of tumor angiogenesis, metastasization, and immune response." (PMID 35498406, 2022). "The secretion of CCL2 has been demonstrated in several cancer cell types, but data in thyroid cancer are scanty." (PMID 29977225, 2018). "Studies taking into account the role of CCL15, C–X–C motif ligand 12, CXCL16, CXCL1, CCL20, and CCL2 in the context of thyroid cancer will be reviewed with particular emphasis on CXCL8." (PMID 29977225, 2018). "Recently, wedescribed a similar NF-κB-dependent co-regulation of QPCT and CCL2 inepithelial cells of thyroid carcinomas upon TNF-α/IL-1β treatment." (PMID 28739588, 2017). "The aim of the present study was to investigate if vitamin D could modulate both thyroid cancer cell migration and their ability to secrete CCL2 and CXCL8." (PMID 35498406, 2022). "Mice were treated with doxycycline for one week to develop thyroid cancer, and the expression levels of CCL2, CSF-1, LGALS3BP, INPP5D and CCL7, together with that of the chemokine receptors CCR2 and CSF1R, were measured in cancer specimens by quantitative RT-PCR." (PMID 34299284, 2021). "CCL2 is overexpressed in liver, breast, gastric, and thyroid cancer 11; CCL5 is overexpressed in gastric, pancreatic, breast, colorectal, prostate, liver, and thyroid cancer 12; CCL7 is markedly upregulated in lung, gastric, colorectal, and uroepithelial cancer." (PMID 33123272, 2020). "In thyroid carcinoma cell lines, QPCT gene expression correlated with the mRNA levels of its substrate CCL2." (PMID 38417050, 2024). "Future studies specifically designed at clarifying the pathways involved in the different inhibitory effects of vitamin D on CCL2 and CXCL8 in thyroid cancer cells appear worthwhile." (PMID 35498406, 2022). "In particular, the secretion of CCL2 was inhibited by vitamin D in both TPC-1 (RET/PTC) and 8505C (BRAFV600e) thyroid cancer cell lines." (PMID 35498406, 2022). "At present, CCL2, CCL15, CCL20, CXCL1, CXCL8, CXCL12, and CXCL16 are the main chemokines showing a role in thyroid cancer." (PMID 29977225, 2018). "We tested the mRNA levels of six more genes, including three with different abundance in antibody array between FTC and FA, two previously reported TAMs recruiters (CCL2 and CCL7), and CSF-1 which was reported as TAMs recruiters in thyroid cancers." (PMID 26875556, 2016). "Furthermore, vitamin D differently modulates the secretion of CCL2 and CXCL8 by thyroid cancer cell lines." (PMID 35498406, 2022). "CCL2 and CXCL8 concentrations were assayed in the supernatants of 8505C thyroid cancer cell lines." (PMID 35498406, 2022). "CCL2 and CXCL8 concentrations were assayed in the supernatants of TPC-1 thyroid cancer cell lines." (PMID 35498406, 2022).
thyroid cancer (continued). "The aim of the present study was to investigate whether vitamin D (1,25-OH2 D3) exerts both direct (cell viability and migration) and indirect (modulation of the pro-tumorigenic chemokines and CXCL8 and/or CCL2 secretion) antitumor effects in TPC-1 and 8505C thyroid cancer cell lines." (PMID 35498406, 2022). "The hypothesis that vitamin D could affect the CXCL8 and/or CCL2 secretion was never tested in thyroid cancer." (PMID 35498406, 2022). "Given that FOXE1 expression induces both CCL2 and CSF1, together with other chemoattractants, in thyroid cells in vitro, we asked if FOXE1 could modulate the oncogenic induction of chemokines and hence the infiltration of thyroid cancer by TAMs in vivo." (PMID 34299284, 2021).
alcoholic liver diseases (12 papers, 2013 to 2026). A disorder caused by damage to the liver parenchyma due to alcohol consumption. "In a mouse model of alcoholic liver disease, HuR was found to play a key role in NOX4 mediated increase in CCL2 mRNA stability." (PMID 37961304, 2025).
amyloid (12 papers, 2009 to 2025). "Opposite results were however observed in a recent study showing that total CCL2 deficiency in the 5xFAD amyloid mouse model, improved cognition during Y-maze, normalized IL-1β and CCL3 levels, reduced astrogliosis and amyloid plaque formation as well as Aβ accumulation and neurodegeneration." (PMID 32508844, 2020). "Our present findings support an increase in amyloidosis following CCL2 overexpression in the brain of APP/PS1 mice." (PMID 32508844, 2020). "Given the contradictory results observed in mouse models of amyloidosis, more studies involving the role of CCL2 signaling concerning tau pathology are needed." (PMID 32508844, 2020). "Transgene expression of CCL2 in mouse models of amyloidosis produces microglia-induced amyloid β oligomerization, a strong indication of the role of these activation pathways in the amyloidogenic processes of AD." (PMID 32508844, 2020). "Indeed, genetic manipulations of CCL2 in a mouse model of amyloidosis led to the worsening of Aβ pathology with both overexpression and deficiency in CCL2." (PMID 32508844, 2020). "However, a recent report showed improved cognition and decreased amyloidosis in 5xFAD/CCL2 null mice, another amyloid mouse model." (PMID 32508844, 2020). "Other studies have indicated that CCL2 expression accelerates amyloidosis in an amyloid precursor protein (APP)/CCL2 bigenic mouse model, suggesting a different role of CCL2 in resident microglia and ultimately the AD pathology of these mice." (PMID 23866683, 2013). "In the absence of CCL2, amyloid pathology is accelerated in an AD mouse model, illustrating its important role in amyloid plaque clearance and pointing to a potentially reparative role in AD." (PMID 25340798, 2014). "In periphery, CCL2 is a key molecule for the CNS recruitment of circulating monocytes, which are 7/4briLy-6G−CCR2+F4/80+ or Ly-6ChiCCR2+, and play a critical role in amyloid clearance." (PMID 19593388, 2009). "Moreover, overexpression of CCL2 driven by GFAP promoter in APP/CCL2 mice enhanced amyloidosis, increased microglial Iba-1immunoreactivity, and decreased cognition while APP/PS1/CCL2 null mice also displayed increased levels of Aβ oligomers and worsening of cognitive dysfunction." (PMID 32508844, 2020).
atrial fibrillation (12 papers, 2017 to 2025). A disorder characterized by an electrocardiographic finding of a supraventricular arrhythmia characterized by the replacement of consistent P waves by rapid oscillations or fibrillatory waves that vary in size, shape and timing and are accompanied by an irregular ventricular response. "Elevated levels of CXCL8, CCL11, CCL2, CXCL10, IL-1β, IL-6, TNF-α, IFN-γ, IL-17, IL-1Ra, IL-4, IL-9, FGF-basic, PDGF, G-CSF, and GM-CSF were observed in the Atrial fibrillation patient, in contrast to uninfected controls." (PMID 29370812, 2018).
carotid atherosclerosis (12 papers, 2010 to 2025). A thickening and loss of elasticity of the walls of carotid arteries that occur with formation of atherosclerotic plaques. "Fibrinogen levels were positively associated with CCA-IMT while ICAM-1, CCL2, and sTNF-αR1 were positively associated with bifurcation-IMT, our secondary measures of subclinical carotid atherosclerosis." (PMID 30946765, 2019). "The biomarker with the most robust association with subclinical carotid atherosclerosis in the present study, based on magnitude, consistency of associations regardless of HIV serostatus, and coherence across carotid measures, was CCL2." (PMID 30946765, 2019). "Despite the signal between the monocyte activation markers and carotid atherosclerosis, the fact that CCL2 and sCD163 were associated with carotid plaque but not with CCA-IMT in our study is, to our knowledge, a novel finding." (PMID 30946765, 2019). "Although CCL2 does not perform well in the lower extremity atherosclerotic artery, it performs well in the carotid atherosclerotic artery and plaque groups, which indicates that CCL2 is a specific immune gene for carotid atherosclerosis and plaque formation." (PMID 35509837, 2022).
Chronic colitis (12 papers, 2015 to 2025). A chronic inflammatory disease of the large intestine (colon, cecum and rectum). "CCL2, the mostly studied CC family gene, was concluded to be a crucial mediator of the initiation and progression of chronic colitis-associated colon carcinogenesis." (PMID 26515597, 2015). "In the tissue with chronic colitis, CCL-2 but not FAPα was also significantly high compared to the control." (PMID 31920487, 2019).